PC (pyruvate carboxylase)
Diseases named in the same sentence as PC in open-access papers (continued):
Sharing a sentence is not in itself a finding about the gene and the disease.
systemic lupus erythematosus (1 paper, 2023). An autoimmune multi-organ disease typically associated with vasculopathy and autoantibody production. "So far, antibodies against thrombin, PC, plasmin, and FXa have been detected in systemic lupus erythematosus (SLE) and antiphospholipid syndrome (APS), allowing researchers to characterize their role in the underlying pathways that lead to disease onset." (PMID 36979885, 2023).
Ta (1 paper, 2025). "In Ta tumors, commonly expressed glycoproteins were primarily associated with metabolic and regulatory activities, including pyruvate carboxylase activity, fatty acid amide hydrolase activity, SUMO binding, and sequence-specific single-stranded DNA binding." (PMID 40430030, 2025).
thrombosis (1 paper, 2026). "During prospective follow-up of 283 patients from the APS ACTION Registry (median 8.3 years), 25/283 (8.8%) had new thrombosis, with similar incidence between patients with or without APCr or anti-PC (p > 0.60)." (PMID 42287725, 2026).
cancer (46 papers, 2014 to 2026). A tumor composed of atypical neoplastic, often pleomorphic cells that invade other tissues. "For a few years, the biotin-dependent enzyme pyruvate carboxylase (PC), which catalyzes the carboxylation of pyruvate to oxaloacetate, has been linked to metabolic reprogramming in multiple cancer models by replenishment of the TCA cycle intermediates." (PMID 38081642, 2024). "Pyruvate carboxylase (PC) is a biotin‐containing enzyme that converts pyruvate to oxaloacetate and has been implicated in cancer progression." (PMID 34609082, 2021). "The pyruvate carboxylase (PC)-mediated anaplerosis pathway for TCA intermediates is implicated in the progression of a variety of cancers." (PMID 34136384, 2021). "Here, we systematically profile the adaptation of SDH-knockout cancer cells and find that cells can adapt to SDH loss via at least two distinct mechanisms: suppression of respiratory complex I or upregulation of pyruvate carboxylase." (PMID 42239110, 2026). "Lactate produced by cancer cells rewires metabolism in CD8+ cells by decreasing pyruvate carboxylase (PC) activity, which is crucial for the anaplerotic replenishment of the TCA cycle and the production/secretion of succinate." (PMID 39438765, 2024). "Some enzymes in the pyruvate metabolic pathway, such as pyruvate kinase (PK) and pyruvate carboxylase, have been studied in cancer." (PMID 37662928, 2023). "It was reported that pyruvate carboxylase was highly expressed in glutamine-independent cancer cells, contributing to maintain anaplerosis under glutamine-deprivation conditions." (PMID 35154470, 2022). "Pyruvate carboxylase (PC) is an important anaplerotic enzyme in the tricarboxylic acid cycle (TCA) in cancer cells." (PMID 34158007, 2021). "Here, we identified PRDM16 exhibited antitumor activities toward cancer cell proliferation and migration by its targeting of pyruvate carboxylase and regulating EMT." (PMID 34796170, 2021). "It was reported that Wnt/β-catenin signaling induced an increase in glucose uptake and suppressed mitochondrial respiration, mechanically activating pyruvate carboxylase to support cancer cells proliferation." (PMID 35083240, 2021). "Specifically, we find that, relative to fibroblasts, cancer cells within PDAC tumors have increased use of glucose for tricarboxylic acid (TCA) cycle anaplerosis through increased flux through pyruvate carboxylase (PC)." (PMID 32648540, 2020). "(H) Expression of pyruvate carboxylase as assessed by qPCR in PDAC cancer cells or PSC cells sorted from organoid co-cultures (3D) or in standard 2D culture as indicated." (PMID 32648540, 2020). "Activation of WNT/β-catenin signaling was shown to promote aerobic glycolysis in cancer cells via suppressing mitochondrial respiration, inducing the activity of pyruvate carboxylase and increasing the expression pyruvate dehydrogenase kinase 122,23." (PMID 31142735, 2019). "Pyruvate carboxylase (PC), an enzyme that convert pyruvate to oxaloacetate, has been proved to play an important role in cancer cell metabolism and proliferation." (PMID 28738810, 2017). "Our analysis also sheds new light on pyruvate carboxylase activity in cancer cells, an issue that has been raised in various tumours." (PMID 27493727, 2016). "While growing evidence have now indicated that glutaminolysis is crucial for many cancers, limited information is available regarding the importance of pyruvate carboxylation via pyruvate carboxylase (PC) in cancers." (PMID 26070193, 2015). "Our present study is the first report to show a strong association between the levels of PC expression in breast tissues of patients and stages of cancer progression (P < 0.05), which suggests PC is involved in metastasis." (PMID 26070193, 2015). "In contrast, low‐invasive OVCA cancer cells have higher pyruvate‐dependent reductive carboxylation flux using pyruvate carboxylase (PC)." (PMID 24799285, 2014).
cancer (continued). "The recent studies with the cultured cancer cells and on the animal models revealed that also the anaplerotic role of pyruvate carboxylase (PC) could significantly participate in sustaining the metabolism and survival of cancer cells and the growth of tumors." (PMID 36662405, 2023). "Additionally, pyruvate carboxylase activity has a function in protecting cancer cells from oxidative damage and regulating lipid metabolism." (PMID 37662928, 2023). "In cancer cells, an increase in lactate concentration and HIF1 activation causes a shift in the direction of metabolic reactions in the Krebs cycle to depend on glutamate by inhibiting pyruvate dehydrogenase (PDH) and pyruvate carboxylase (PC)." (PMID 35745875, 2022). "PC-PLC inhibition and exogenous NO delivery have both been shown to be decrease the activity of NF-κB, a transcription factor involved in the regulation of various genes associated with cancer cell survival, proliferation, angiogenesis, and metastasis." (PMID 34768947, 2021). "Pyruvate carboxylase (PC) is a major anaplerotic enzyme that catalyzes the carboxylation of pyruvate to form oxaloacetate, which has been suggested to be involved in the tumorigenesis of several cancers, including PTC." (PMID 34136384, 2021). "The enzyme pyruvate carboxylase (PC) contributes to cellular energy metabolism through converting pyruvate to oxaloacetate (OAA) and has been associated with metabolic reprogramming and increased tumor progression in a variety of cancer models." (PMID 33931119, 2021). "Assessment of pyruvate carboxylase activity in PDAC cancer cells and fibroblasts." (PMID 32648540, 2020). "Pyruvate carboxylase in cancer cells is required for PDAC tumor growth in vivo." (PMID 32648540, 2020). "Despite the fact that glutamine inhibitors may reduce the replenishment of the TCA cycle intermediates, cancer cells may develop “resistance” by the upregulation of pyruvate carboxylase (PC)." (PMID 30634602, 2019). "The role of anaplerotic nutrient entry into the Krebs cycle via pyruvate carboxylase has been the subject of increased scrutiny and in particular whether this is dysregulated in cancer." (PMID 27493727, 2016). "In addition to be the entry point of the Krebs cycle, OAA is the product of the anaplerotic reaction catalyzed by pyruvate carboxylase (PC), which is important in some cancers." (PMID 25628363, 2015). "For example, conditions of limited glutamine availability or glutaminase (GS) suppression drive cancer cells to increasingly rely on glucose carbon flux through pyruvate carboxylase (PC) to maintain oxaloacetate (OAC) production and downstream TCA cycle activity." (PMID 25621173, 2015). "Similarly, overexpression of pyruvate carboxylase in certain cancer types and the production of OAA have been shown to mediate gluconeogenesis-like anabolic fluxes by directing NAD+ regeneration, aspartate biosynthesis, and serine/glycine/phospholipid metabolism." (PMID 41142618, 2025). "Another is pyruvate carboxylase (PC), which can have increased expression and activity in SDH-null cancer cells." (PMID 36883551, 2023). "Taken together, these data demonstrate roles for PKM2, PC and PCK2 in HCC, which links metabolic flux and anabolic pathways to cancer cell proliferation." (PMID 28378759, 2017). "Recent evidence has shown that cancer cells can engage glutamine metabolism enzymes, such as PEP-carboxykinase (PCK2) or pyruvate carboxylase (PC), to develop metabolic adaptation and promote enhanced cell growth when even glucose is limited." (PMID 27409831, 2016). "Cancer cells also have altered means to replenish the TCA cycle, for instance via pyruvate carboxylase (PC) or enhanced levels of glutaminase (GLS) driven by Myc expression." (PMID 25250177, 2014). "Cancer cells boost glucose uptake via transporters (GLUT1/3), channeling pyruvate and lactate into the TCA cycle through pyruvate dehydrogenase (PDH) or pyruvate carboxylase (PC)." (PMID 40734168, 2025).
cancer (continued). "PC is a biotin-dependent enzyme that catalyzes the carboxylation of pyruvate to oxaloacetate, aiming to replenish the TCA cycle, and its activity has been shown to promote metabolic reprogramming in several malignant tumor progressions." (PMID 38081642, 2024). "The Cancer-Induced Lactate Load and Oncologic Remodeling (CILLO) hypothesis proposes that lactate, either imported through MCT1 or produced endogenously, is oxidized to pyruvate by LDHB and subsequently carboxylated to oxaloacetate (OAA) by pyruvate carboxylase." (PMID 41142618, 2025). "We raise for the first time that metformin may inhibit pyruvate carboxylase flux, indicated by decreased m1 but increased m2 in glutamate, TCA cycle output and likely ATP production (not measured) in the CHS-MIA PaCa-2 cancer cell line." (PMID 24482631, 2014).
tumor (40 papers, 2009 to 2025). "Another anaplerosis-associated enzyme, pyruvate carboxylase (PC) is highly expressed in the tumor compared to the surrounding brain." (PMID 33567690, 2021). "For instance, pyruvate carboxylase (PC) enables aspartate synthesis in SDH-deficient tumor cells, creating a metabolic vulnerability." (PMID 30197878, 2018). "Moreover, PC is the only enzyme that is significantly associated with tumor inflammatory infiltration." (PMID 37894303, 2023). "In tumours with AKT1E17K/TRAF7 mutations, specific antibodies were available for four up-regulated proteins (CLIC3, CRABP2, GMDS, and Pyruvate carboxylase)." (PMID 40562609, 2025). "For example, lactate secreted by tumor cells alters the metabolism of CD8+ T cells by inhibiting pyruvate carboxylase (PC) activity, weakening their cytolytic activity." (PMID 38835341, 2024). "In recent studies on NSCLC, LncRNA-CTD-2245E15.3 exerts its carcinogenic function by binding ACC1 and pyruvate carboxylase (PC), which are key anabolic factors in biomolecule synthesis in rapidly proliferating tumor cells." (PMID 36452489, 2022). "Our model predicts that tumor cells that synthesize fatty acids de novo must increase their glutamine uptake or upregulate the expression of the enzyme PC." (PMID 35148308, 2022). "Overexpression of GCASPC lncRNA decreased PC protein expression and activity, cell proliferation, and tumor growth in vivo, and proliferation was rescued when PC was overexpressed." (PMID 33931119, 2021). "In fact, mutations within the PC, PRICKLE2 and TSC2 genes have previously been associated with non-neurodegenerative diseases including diseases involved in energy deficiency, tumour formation and seizures." (PMID 32019516, 2020). "Pyruvate carboxylase increased activity has been reported as a potential metabolic mechanism for tumor growth in situations where GLS activity is challenged However, a decrease in lactate levels with metformin or combination treatment was observed via NMR." (PMID 32158544, 2020). "PC activation in tumor tissues was also shown by an increased level of pyruvate carboxylase mRNA and protein." (PMID 19558692, 2009). "This metabolic change not only hinders CD8+ T cells’ ability to function normally by depriving them of vital glucose, but the accumulated lactate can also further disrupt CD8+ T cells’ TCA cycle by inhibiting pyruvate carboxylase (PC), which reduces their anti-tumor activity." (PMID 39776907, 2024). "Moreover, pyruvate carboxylase expression was decreased, which is needed for glutamine-independent growth of tumor cells, since this enzyme allows these cells to use glucose-derived pyruvate rather than glutamine for anaplerosis." (PMID 37509679, 2023). "Increased activity of pyruvate carboxylase has been reported as a potential metabolic mechanism for tumor growth in situations where GLS activity is challenged, although growing the cells in glucose-free media for 72 h did not affect significantly the viability nor the growth of CB839-treated cells." (PMID 33101674, 2020). "Interestingly, PC expression showed a significant correlation with the tumor size (P = 0.033) i.e., PC was poorly expressed in most tumor cases with small volume (<4 cm3) (86%, 25/29)." (PMID 26070193, 2015). "Tumor‐derived lactate can induce a pyruvate utilization switch in CD8+ T cells, enhancing pyruvate carboxylase (PC) utilization instead of pyruvate dehydrogenase (PDH)." (PMID 40223597, 2025). "Inhibition of PDH restores pyruvate carboxylase (PC) activity, leading to increased succinate secretion, which activates SUCNR1 signaling and boosts CD8+ T cell cytotoxic function, counteracting tumor-induced immunosuppression." (PMID 41441035, 2025). "For example, Kras-driven NSCLC tumor formation and growth are completely abrogated by PDHA or PC knockout." (PMID 39695108, 2024).
tumor (continued). "Manganese plays an important role in the anti-tumor immune response of cGAS-STING, which can improve the efficacy of clinical immunotherapy and is involved in some enzymes, such as pyruvate carboxylase and arginase in mitochondria." (PMID 38004195, 2023). "This study revealed significant differences in the expression of three specific enzymes—pyruvate carboxylase (PC), phosphoenolpyruvate carboxykinase (PCK), and fructose-1,6-bisphosphatase (FBP)—among tumor cells when stratified by MS and mBMI." (PMID 37894303, 2023). "We observed significant differences in pyruvate carboxylase (PC), phosphoenolpyruvate carboxykinase (PCK), and fructose-1,6-bisphosphatase (FBP) tumor cell expression when stratified by MS and mBMI." (PMID 37894303, 2023). "The tumor cell expression of enzymes catalyzing the irreversible reactions of glycolysis (HK, PFK, and PK) and gluconeogenesis (PC, PCK, FBP, and G6P) was investigated by immunohistochemistry." (PMID 37894303, 2023). "Quantitative immunohistochemical analysis of tumor xenografts from nude mice showed that TSHR, NIS, TPO, and TG expression were all significantly reduced after overexpression of PC." (PMID 36266265, 2022). "Moreover, the glutaminolytic enzyme GLUD1 (glutamate dehydrogenase 1) and pyruvate carboxylase, an enzyme interconverting OAA and pyruvate, were clearly expressed in macrophages from normal lung, while their expression was less prominent in tumor macrophages." (PMID 41160607, 2025). "However, the reaction catalyzed by pyruvate carboxylase (PC), generating oxoloacetate (that condenses with acetyl-coA to form citrate, which enters the TCA cycle) from pyruvate, is downregulated in most neoplasms." (PMID 32013066, 2020). "The results showed that CLDN9, AK4, PC, GPC1, and SRD5A3 were upregulated in EC tissues compared to in normal endometrium tissues, whereas B4GALT1, GMPPB, B4GALT4, and CHST6 were downregulated in tumor tissues." (PMID 31807118, 2019).
infection (10 papers, 2010 to 2025). The state of being infected such as from the introduction of a foreign agent such as serum, vaccine, antigenic substance or organism. "Furthermore, the expression level of pyruvate carboxylase (PC) was only down-regulated after pathogen infection in the hemocytes of V. parahaemolyticus-susceptible shrimp." (PMID 38785782, 2024). "Interestingly, our results showed that virus stimulation caused cytoplasmic translocation of PC after infection for 12 h in A549 cells, and similar results were observed in 293T cells." (PMID 26906558, 2016). "On the other hand, several genes associated with gluconeogenesis (e.g. pyruvate carboxylase, a pyruvate kinase, two glucose-6-phosphate, and others) were expressed only in Trincadeira and are likely associated with fungal proliferation after successful infection." (PMID 36479580, 2022). "We validated our findings genetically, focusing on pyruvate carboxylase, which was identified across multiple studies and was confirmed here to be important across all infection models studied." (PMID 34101490, 2021). "As deep validation of these hypotheses, we investigated the role of pyruvate carboxylase, which was important across multiple infection models and confirmed a connection between growth and resistance to host cell killing." (PMID 34101490, 2021). "Pyruvate carboxylase is important across multiple infection sites." (PMID 34101490, 2021).
genetic disorder (3 papers, 2005 to 2024). "Pyruvate carboxylase (PC) enzyme deficiency is a rare genetic disorder inherited in an autosomal recessive (AR) manner." (PMID 36348915, 2022). "It should be noted, however, that genetic disorders in humans in which the activity of pyruvate carboxylase is reduced results in the development of a fatty liver, suggesting that a failure of anaplerosis can also result in hepatic fat accumulation." (PMID 16300682, 2005).
metabolic disorders (3 papers, 2025). "Pyruvate carboxylase (PC), a mitochondrial enzyme involved in glucose metabolism, is implicated in various metabolic disorders; however, its role in AS remains unclear." (PMID 40391718, 2025). "Pyruvate carboxylase is a key manganese-dependent enzyme and is relevant in the context of metabolic disorders." (PMID 40007873, 2025).
psychiatric disorder (1 paper, 2020). A disorder characterized by behavioral and/or psychological abnormalities, often accompanied by physical symptoms. "Gene-based association tests for the 42 DNV-bearing genes implicated haptoglobin (HP) and pyruvate carboxylase (PC), 2 brain-expressed genes associated across 3 psychiatric disorders that carry potentially pathogenic DNVs." (PMID 32383744, 2020).
PC also shares sentences with these, for which no sentence is quoted: glioblastoma (4 papers); Papillary Thyroid Cancer (4); colon cancer (3); ischemia (3); Astrocytomas (2); Hepatic steatosis (2); non-small cell lung carcinoma (2); Pyruvate carboxylase deficiency (2); venous thromboembolism (2); acute myeloid leukaemia (1); Angelman syndrome (1); antiphospholipid syndrome (1); Anxiety (1); argininosuccinic aciduria (1); Arterial thrombosis (1); autism (1); bladder cancer (1); Cerebral ischemia (1); colon (1); depression (1); diabetes mellitus type 1 (1); haemophilia (1); Hepatitis (1); holocarboxylase synthetase deficiency (1); Hyperammonemia (1); hypertriglyceridemia (1); infectious disease (1); insulinoma (1); intestinal inflammation (1); leukaemia (1).
A further 24 diseases each share a sentence with PC in 1 paper.